KL (klotho)
Diseases named in the same sentence as KL in open-access papers (continued):
Sharing a sentence is not in itself a finding about the gene and the disease.
kidney damage (52 papers, 2013 to 2025). "A comparable association was observed in a study on the association between serum klotho concentration and cognitive ability in elderly patients with nephropathy and proteinuria, which also demonstrated an initial increase followed by a subsequent decrease." (PMID 39563739, 2024). "The term Klotho describes a gene and an associated protein that is involved in numerous processes in health and disease (e.g., ageing, kidney damage, cardiovascular disease) and is therefore of increasing interest." (PMID 38787156, 2024). "As Klotho is kidney protective, its deficiency defines a permissive setting for the development and progression of nephropathies after injury." (PMID 38164143, 2024). "Klotho is rapidly downregulated when kidneys are injured, making this factor a marker of early kidney damage, and associated with the aging and cellular senescence in the kidney." (PMID 35204184, 2022). "We also found that Klotho upregulated autophagy activity and rescued phenotypes, including the reduction of plasma phosphate and attenuation of ischemia-induced kidney damage in autophagy-deficient mice." (PMID 33915953, 2021). "The abnormal increase in serum creatinine and urea in Klotho-deficient mice also induce kidney damage; however, the changes were insignificant in WT mice." (PMID 33767585, 2021). "We previously demonstrated that Tac-induced nephropathy caused downregulation of renal Klotho, and drugs with antioxidant potential such as statin, angiotensin II blockade, and N-acetylcysteine, increased Klotho expression." (PMID 28771227, 2017). "Ithas been shown that the expression of the antiaging klotho proteinis downregulated in the IS-stimulated proximal tubule cells and kidneys,but the detailed mechanism underlying the implication of reduced klothoin nephropathy remains largely unclear." (PMID 40547630, 2025). "A critical factor in the development of kidney damage is reduced Klotho, which may be linked to podocyte pyroptosis in DKD." (PMID 40119098, 2025). "Additionally, there are reviews suggesting that Klotho deficiency can also be a causative factor in the progression of kidney damage." (PMID 36675565, 2023). "As loss of Klotho is a common feature of various nephropathies or advanced age, this prompted us to hypothesize that a state of Klotho deficiency may sensitize mice to developing COVID-19-associated AKI." (PMID 38239193, 2023). "Therefore, a reduction in Klotho is strongly associated with kidney dysfunction and may contribute to kidney damage." (PMID 40869353, 2025). "Klotho gene delivery through a viral carrier has been shown to effectively improve multiple pathophysiological phenotypes in klotho-deficient mice, thereby preventing the progression of kidney damage in rat models and improving VC and endothelial function in CKD." (PMID 30348110, 2018). "Meanwhile, deteriorating kidney function significantly reduces Klotho production, consequently exacerbating inflammatory responses and kidney damage." (PMID 40519908, 2025). "Klotho is a promising target for future nephropathy treatments, addressing issues such as oxidative stress, mitochondrial abnormalities, and cell aging." (PMID 38812032, 2024). "Being involved in various physiological and pathophysiological mechanisms (ageing, kidney damage, cardiovascular diseases, etc.), Klotho is a parameter of increasing interest." (PMID 38787156, 2024). "We first assessed the expression of Klotho protein in various animal models of nephropathies induced by IRI, UUO and 5/6NX, as well as in db/db or old mice, respectively." (PMID 38239193, 2023). "Klotho has anti-inflammatory antifibrotic and antiaging properties and Klotho administration was protective in several experimental nephropathies." (PMID 37958836, 2023).
kidney damage (continued). "Our study proposed that the detection of Klotho should be taken into consideration in the early stage of kidney damage, and clinicians should incorporate Klotho detection into routine assessments for older CKD patients aiming at cognitive enhncement." (PMID 37560310, 2023). "Klotho administration ameliorated mitochondrial dysfunction in an FK506-induced nephropathy mice model and in FK506-treated HK-2 cells." (PMID 36829798, 2023). "As Klotho expression decreases with increasing kidney damage, stabilization of Klotho via nanobodies would represent a promising approach for individualized patient treatment." (PMID 34131806, 2021). "Studies with rodents demonstrated that these drugs led both to an increase in renal Klotho levels and to the attenuation of the reduction of Klotho in nephropathy." (PMID 35056905, 2021). "We next investigated the mechanism by which Klotho overexpression revered IS-induced heart failure and kidney damage." (PMID 32464602, 2020). "Recent advances in understanding KLOTHO biology definitely support the notion that aberrant function of the protein promotes nephropathy progression and CVD development." (PMID 32435919, 2020). "We have demonstrated that overexpression of Klotho promotes M2 macrophage polarization to alleviate heart failure and kidney damage in mice by inactivating the NF-kB pathway." (PMID 32464602, 2020). "Evidence suggests that renal and systemic klotho and sirtuin 1 (SIRT1) deficiencies worsen kidney damage induced by exogenous stresses." (PMID 32942691, 2020). "In an experimental model of TAC-induced nephropathy, we found that concomitant Klotho treatment inhibits the PI3K/AKT-mediated phosphorylation of FoxO3a and enhances FoxO3a binding to the MnSOD promoter." (PMID 31772699, 2019). "Our finding of decreased Klotho expression in the kidney of ZDF rats during overt nephropathy is in agreement with findings of decline of renal Klotho both in rodent models of chronic renal damage and patients with CKD." (PMID 23967103, 2013). "Furthermore, Klotho alleviates cyclosporine A-induced nephropathy in vivo and in vitro models by blocking the PDLIM2/NF-κB pathway, which reduces the level of IL-8, IL-6, and IL-12." (PMID 40119098, 2025). "The antiaging factor klotho is downregulated in response to kidney damage." (PMID 40573218, 2025). "In vitro and in vivo, Klotho overexpression reduces kidney damage and heart failure by inhibiting the IS-induced inflammatory response macrophage polarisation by raising the anti-inflammatory factor IL 10, lowering pro-inflammatory cytokines, and deactivating the NF-κB pathway." (PMID 40119098, 2025). "Additionally, LC treatment promoted macrophage polarization towards the anti-inflammatory phenotype, downregulated GDF-15 expression, upregulated Klotho expression, and ameliorated kidney damage." (PMID 40362229, 2025). "Further, Klotho values in AKI patients were found to be greater compared to CKD, reflecting acute kidney damage in AKI patients as compared to chronic damage in CKD due to progressive loss of kidney damage." (PMID 41394384, 2025). "As such, restoring Klotho expression could be a logic strategy for protecting against various nephropathies." (PMID 38164143, 2024). "Aging-associated kidney damage has been linked to upregulated endothelin A receptor, interleukin-6, and NADPH oxidase 2 expression as well as the generation of superoxide and downregulation of klotho, the ET B receptor, and manganese superoxide dismutase." (PMID 37507979, 2023). "The upregulation of TFEB by Klotho could explain some of the described beneficial effects of this protein in the FK506-induced nephropathy models." (PMID 36829798, 2023). "Furthermore, BL administration markedly increased the expression of Klotho, which was detected as being reduced when kidney damage occurred." (PMID 36360095, 2022). "For example, klotho replacement therapy in AKI mice resulted in reduced kidney damage." (PMID 35351833, 2022).
kidney damage (continued). "In the present study, we investigated whether in Klotho-deficient mice treated with BSA, the changes in intestinal microflora structure and effects on the immune system induce kidney damage and CKD." (PMID 33767585, 2021). "The results indicate that in absence of Klotho expression in mice, small doses of albumin stimulation for a long time keep burdening the kidney, causing kidney damage." (PMID 33767585, 2021). "Our findings indicate overexpression of Klotho in macrophages can restore IL-10 expression and promote macrophage M2 polarization in kidney and heart tissue to alleviate IS-induced heart failure and kidney damage." (PMID 32464602, 2020). "We recently reported that chronic CNI nephropathy is a state of excessive accumulation of autophagosome and impaired autophagy clearance and Klotho treatment reduces the burden of autophagy vacuoles by improving autophagy clearance via activation of lysosomal function in CNI-induced nephrotoxicity." (PMID 31772699, 2019). "However, as the disease progresses, the severity of nephropathy increases, and serum Klotho levels may decrease again." (PMID 34670596, 2021). "Overexpression of Klotho downregulated IS-induced phosphorylation of NF-kB p65 in vitro and in vivo, also suggesting that Klotho overexpression could alleviate heart failure and kidney damage by inactivating the NF-kB pathway." (PMID 32464602, 2020). "Indeed, Klotho heterozygous mice showed aggravated Tac-induced nephropathy." (PMID 31400753, 2019). "In addition, we discuss the delivery strategy for Klotho in CNI-induced nephropathy." (PMID 31772699, 2019). "Furthermore, to confirm kidney damage in our experimental model, we measured the expression levels of kidney injury molecule-1 (KIM-1) and NGAL (neutrophil gelatinase-associated lipocalin), both considered kidney damage markers, as well as renal Klotho mRNA expression." (PMID 36674838, 2023). "In NRK-49F cells, we also found that lotensin and Nephropathy 1st reversed the effects of TGF-β1 on the expression of Col-I, FN, PPARγ, and Klotho." (PMID 36339588, 2022). "Studies have demonstrated that Klotho production is reduced in different models of AKI, such as in cisplatin-induced AKI and AKI induced by IRI, which contributes to kidney damage during this disease." (PMID 35056905, 2021). "We used small doses of BSA (the dose of BSA reported to induce kidney damage in mice is approximately 10-15 mg/g 31, but we selected a dose 1/10 of this dose) to achieve drug-induced kidney injury in mice to investigate whether Klotho mice are more prone to drug-induced kidney damage than WT mice." (PMID 33767585, 2021). "Using an experimental model of chronic CNI nephropathy, we found that CNI treatment decreased Klotho protein in a dose- and time-dependent manner, and Klotho deficiency aggravated CNI-induced oxidative stress." (PMID 31400753, 2019). "Lotensin and the medium and high concentrations of Nephropathy 1st increased the levels of PPARγ and klotho in TGF-β1-challenged fibroblasts, suggesting that PPARγ might be involved in the therapeutic effect of Nephropathy 1st." (PMID 36339588, 2022). "Circulating FGF23 was reported increased and klotho decreased in AKI rodent models, and treatment with klotho could improve kidney damage." (PMID 35272698, 2022). "Notably, the expression of the antiaging gene klotho is reduced in the onset of DKD, which exacerbates the early nephropathy." (PMID 28929120, 2017). "In summary, the complex pathophysiologic mechanisms suggested that Klotho downregulation is not merely an early biomarker for kidney damage, but also one of the principal complications of CKD and may play a pathogenic role in CKD progression." (PMID 36675565, 2023). "Our results infer that the accumulating Klotho due to a severe kidney damage could not benefit for a better cognitive function." (PMID 37560310, 2023).
kidney damage (continued). "Furthermore, it is also possible that KP1 may protect against nephropathies via other mechanisms independent of Klotho expression." (PMID 38164143, 2024).
osteoporosis (52 papers, 2011 to 2025). A condition of reduced bone mass, with decreased cortical thickness and a decrease in the number and size of the trabeculae of cancellous bone (but normal chemical composition), resulting in increased fracture incidence. "Animal studies have revealed that Klotho-deficient mice exhibit multiple accelerated aging phenotypes, including shortened lifespan, arteriosclerosis, skin atrophy, osteoporosis, and cognitive impairment." (PMID 38501099, 2024). "A diet high in phosphorus fed to mice deficient in klotho, a cofactor that regulates phosphate metabolism, accelerates aging, sarcopenia, general organ atrophy, kyphosis, and osteoporosis." (PMID 36557322, 2022). "The aging process in Klotho-deficient mice resembled that in humans, including a shorter lifespan, infertility, arteriosclerosis, skin atrophy, osteoporosis, and emphysema." (PMID 34830314, 2021). "Klotho-deficient (Klothoa−/−) mice revealed systemic age-related abnormalities, such as walking disorders, emphysema, osteoporosis, arteriosclerosis, hypomyelination, hippocampal neurodegeneration and cognitive deficits." (PMID 34763683, 2021). "For instance, Klotho-deficient mice exhibit a shortened life span, skin and muscle atrophy, cognitive impairment, osteoporosis, and hearing loss, resembling an accelerated aging phenotype." (PMID 32457738, 2020). "Among them, Klotho-deficient mice exhibit multiple aging phenotypes including osteoporosis, emphysema, arteriosclerosis, and atrophy in major organs including the sex organs, skin, and pituitary, whereas overexpression of Klotho extends the lifespan of mice." (PMID 29572511, 2018). "Many researchers have recently demonstrated an association between single nucleotide polymorphisms of the klotho gene and age‐related disorders, including coronary artery disease, senile osteoporosis, and stroke." (PMID 28885690, 2018). "FGF23 signals via a complex of anFGF receptor (FGFR1(IIIc)) and Klotho; mice with a loss-of-functionmutation in Klotho develop osteoporosis amongst otherabnormalities, and modest evidence of association of Klotho withBMD has been reported in several studies." (PMID 21533022, 2011). "In addition, clinical studies have reported that decreased S-Klotho levels are associated with the occurrence of a range of aging-related diseases such as cognitive impairment, frailty, osteoporosis, and increased mortality." (PMID 39556550, 2024). "In humans, total Klotho protein levels decline with age in serum, while single nucleotide polymorphisms have been identified in the klotho gene that correlates with reduced longevity and the pathophysiology of age-related disorders such as osteoporosis, coronary artery disease, and stroke." (PMID 29250031, 2017). "KL gene mutation or deletion can result in various phenotypes similar to human aging, such as shortened life span, arteriosclerosis, reduced immune function, and osteoporosis." (PMID 25027542, 2014). "1,25-dihydroxyvitamin D3 (1,25D3) was reported to induce premature organismal aging in fibroblast growth factor-23 (Fgf23) and klotho deficient mice, which is of main interest as 1,25D3 supplementation of its precursor cholecalciferol is used in basic osteoporosis treatment." (PMID 22242193, 2012). "This study evaluated three KLOTHO polymorphisms, namely G395A, C1818T, and C370S, in an elderly population (mean age of 73 years) and their associations with ageing-related outcomes (cardiovascular events, kidney function, osteoporosis, sarcopenia) and mortality." (PMID 32444684, 2020). "The Klotho gene has been reported to regulate calcium and phosphorus metabolism and the pathogenesis of osteoporosis and articular subchondral sclerosis." (PMID 39556550, 2024). "Research has unveiled that mice with impaired Klotho gene expression exhibited blood vessel calcification, growth retardation, and osteoporosis." (PMID 38385060, 2024).
osteoporosis (continued). "Klotho mice are models of premature aging and exhibit aging-related phenotypes such as osteoporosis and short lifespan." (PMID 35050204, 2022). "Klotho-deficient mice exhibit reduced lifespan, skin and muscle atrophy, osteoporosis and ectopic calcification whereas Klotho overexpression increased lifespan." (PMID 32784471, 2020). "Other murine models of progeria (e.g. Lamin A- and Zmpste24-deficient, Wrn−/−, Terc−/−, PolgAmut/mut, Klotho−/−, PolG and XPD strains) also do show osteoporosis." (PMID 31553309, 2019). "Serum Klotho protein levels in the osteoporosis group were clearly lower than those in the normal bone mass group and osteopenia group (P < 0.05)." (PMID 29665846, 2018). "In the present study, serum Klotho protein levels in the patients with osteoporosis in the femoral neck were lower than those of the group with osteopenia and normal bone mass in the femoral neck." (PMID 29665846, 2018). "Loss-of-function Enpp1ttw/ttw mice under phosphate overload conditions exhibited phenotypes resembling human aging and Klotho mutants, such as short life span, arteriosclerosis and osteoporosis, with elevated serum 1,25(OH)2D3 levels." (PMID 28798354, 2017). "We hypothesized that AR could modulate the VD/FGF23/Klotho signaling pathway to alleviate osteoporosis." (PMID 34304712, 2021). "The principle function of Klotho, which acts in the FGF 23 signaling, is mainly implicated with calcium, phosphate, and Vitamin D metabolism, explaining the central involvement in aging-related-vascular calcification and osteoporosis." (PMID 32457738, 2020). "Moreover, KL−/− mice experience growth retardation, hypokinesis, osteoporosis, shorten lifespan, while KL transgenic mice exhibit increasing resistance to insulin and extending lifespan." (PMID 32571212, 2020). "The Klotho mouse, which lacks klotho, a transmembrane and secreted β-glucuronidase involved in regulating insulin sensitivity among other functions, displays an accelerated aging phenotype, including short lifespan, infertility, arteriosclerosis, skin atrophy, osteoporosis, and emphysema." (PMID 24757526, 2014). "Klotho is a newly found anti-aging gene and was originally identified in klotho homozygous mutant mice (kl-/-) which showed a human-like aging-related syndrome and develop multiple disorders such as hypogonadism, ectopic calcification, osteoporosis, skin atrophy, and pulmonary emphysema." (PMID 23437382, 2013). "Furthermore, Klotho can interact with vitamin D and fibroblast growth factor (FGF) family members involved in regulating calcium-phosphate metabolism balance, and deficiency or reduction of Klotho may lead to osteoporosis." (PMID 38287280, 2024). "We investigated the therapeutic effect of AR on osteoporosis using SAMP6 mice as experimental material and examined the gene and protein expression content of VD/FGF23/Klotho signaling pathway." (PMID 34304712, 2021). "Mice lacking KL display multiple aging-like phenotypes including vascular calcification and osteoporosis and died prematurely at around two to three months of age, and overexpression of the KL gene extends life span in mice." (PMID 35992154, 2022). "Serum Klotho protein levels in MHD patients with osteoporosis were lower than those of MHD patients without osteoporosis, and these levels were positively correlated with changes in BMD." (PMID 29665846, 2018). "Mice lacking the Klotho protein exhibited severe osteoporosis, depleted numbers of osteoblasts, decreased alkaline phosphatase activities, potentially weakened bone formation, and a large nonmineral region in trabeculae and metaphysis of bone." (PMID 29665846, 2018).